ILK (integrin linked kinase)
Diseases named in the same sentence as ILK in open-access papers (continued):
Sharing a sentence is not in itself a finding about the gene and the disease.
breast cancer (continued). "T315, an integrin-linked kinase (ILK) inhibitor, has been shown to suppress the proliferation of breast cancer, stomach cancer and chronic lymphocytic leukemia cells." (PMID 27537872, 2016). "In breast cancer, T315 suppressed γ-secretase-mediated Notch1 activation in caveolae of IL-6-abundant cells through inhibition of ILK." (PMID 27537872, 2016). "AE suppressed YB-1 expression through the downregulation of ILK/Akt/mTOR-regulated Twist expression in HER-2-overexpressing breast cancer cells." (PMID 27391337, 2016). "In a breast cancer model, pharmacologic inhibition of ILK with QLT0267 was shown to be synergistic with docetaxel, demonstrating enhanced cytotoxic activity, significantly reduced tumor growth, and enhanced survival compared to either agent alone." (PMID 26959113, 2016). "The mouse mammary tumour virus (MMTV) oncogene-induced breast cancer model has been used to address the role of ILK in cancer progression." (PMID 26349061, 2015). "In contrast to our findings that untransformed MECs use Rictor to activate PKC-alpha and Rac1-mediated invasion, breast cancer cells used Rictor to drive motility through protein kinase C-zeta (PKC-zeta;), integrin-linked kinase (ILK;) and Akt." (PMID 26132202, 2015). "Time-lapse microscopy using MDA-MB-231 (breast cancer cells wild-type for the Rb gene product) indicate that ILK inhibition prevented successful bipolar division, resulting in mitotic arrest and either subsequent exit from mitosis or cell death." (PMID 24911651, 2014). "These experiments are particularly important as activated Akt1 does not induce tumors in mice but overexpression of ILK does, and ILK has been shown to play a critical role in MMTV-Neu mouse mammary tumors." (PMID 21646685, 2011). "Transactivations of ER-α machinery, as well as the enhancement in nuclear accumulation of β-Catenin also support the observed upregulation of cyclin D1 in Wnt1/ILK double-transgenic mammary tumors." (PMID 20565980, 2010). "In light of our recent findings and to investigate the potential interaction between Wnt and ILK proteins during mammary tumor formation and progression, we established a transgenic mouse model that expresses both Wnt and ILK in mammary epithelial cells." (PMID 20565980, 2010). "The Wnt1/ILK transgenic model of mammary tumor development shows evidence of expansion of the luminal progenitor cells with a highly active ER-α transcriptional network." (PMID 20565980, 2010). "To begin investigating the cooperation between ILK and Wnt signaling pathways in mammary tumor formation we needed to determine how overexpression of ILK would affect Wnt1-induced mammary tumor development." (PMID 20565980, 2010). "Here, we report novel crosstalk between ILK and Wnt1 oncogenes, resulting in accelerated breast cancer development with molecular characteristics consistent with a more-aggressive phenotype in vivo." (PMID 20565980, 2010). "Recent evidence indicates that ILK expression is increased in various tumours, including prostate cancer, colon cancer, gastric cancer, ovarian cancer, Ewing's sarcoma, melanoma and breast cancer." (PMID 20736946, 2010). "Although cyclin D1 levels were increased in Wnt1 tumors compared with normal mammary epithelium, we found an additional fourfold increase in the cyclin D1 level in Wnt/ILK double-transgenic mammary tumors." (PMID 20565980, 2010). "Western-blot analysis of β-catenin showed greater than twofold increase in β-catenin expression in Wnt/ILK double-transgenic tumors compared with Wnt1-induced mammary tumors." (PMID 20565980, 2010). "In this study, we showed that mammary-specific expression of ILK in MMTV-Wnt1 mice results in the accelerated development of the spontaneous mammary tumors." (PMID 20565980, 2010). "Expression profiling, by microarray DNA analysis, revealed a marked upregulation in FOXA1 in mammary carcinomas of the Wnt/ILK double-transgenic mice." (PMID 20565980, 2010).
breast cancer (continued). "With specific respect to breast cancer, over-expression of ILK in mammary cells stimulates anchorage-independent cell growth, cell cycle progression, and increased cyclin D and A expression in vitro." (PMID 19409087, 2009). "In breast cancer cells, ILK upregulation confers resistance to anoikis, increases tumour invasion, and rapidly induces Snail1." (PMID 19604397, 2009). "The results from these studies indicated that overexpression of ILK not only resulted in the formation of multiple hyperplastic foci but as well a number of the transgenic mice developed focal mammary tumours." (PMID 12771992, 2003). "Our study, to the best of our knowledge is the first to explore ECM remodeling by different stromal cells in 3D breast cancer model and how they could influence the response to an ILK inhibitor." (PMID 41537745, 2026). "We also hypothesize that the pro‐tumorigenic signaling pathways of MSCs and HNLFs are probably distinct and the dependence on ILK in stromal cells is thought to differ based on breast cancer subtype." (PMID 41537745, 2026). "Moreover, ILK inhibitor treatment holds promise for breast cancer therapy particularly in chemotherapeutic resistant cases." (PMID 41537745, 2026). "QLT0267 is a drug that targets ILK and is pre-clinically tested against breast cancer." (PMID 40001469, 2025). "Similarly, HIF1α interacts with integrin-linked kinase (ILK) by establishing a mediating loop and inducing ILK expression to enhance EMT in prostate and breast cancer cells." (PMID 38361941, 2024). "Moreover, under hypoxic conditions, OPN modulates HIF1α-induced VEGF expression via the ILK/NF-κB signaling cascade, which ultimately culminates in breast cancer progression and angiogenesis." (PMID 39062100, 2024). "Meanwhile, the results of mouse models also showed that the combination of GDC-0941 and ILK inhibitor could enhance the therapeutic effect of GDC 0941 on breast cancer." (PMID 35477364, 2022). "Other significant pathways included pathways implicated in breast cancer, among them: actin cytoskeleton, the role of BRCA1 in DNA damage response, paxillin, UVA-induced MAPK, aryl hydrocarbon receptor, ILK, and the molecular mechanisms of cancer-signaling pathways." (PMID 36360779, 2022). "Furthermore, inhibition of ILK/Rictor formation promotes MDA-MB-231 breast cancer cells undergoing the reverse mesenchymal-epithelial transition, inducing MDA-MB-231cells from an aggressive mesenchymal phenotype to a normalized epithelial phenotype 24." (PMID 35982899, 2022). "NET-DNA-mediated stimulation of breast cancer cells resulted in activation of a NET-CCDC25-ILK signaling axis resulting in the activation of the migration/invasion promoting Rho family GTPases, Rac, and cdc42, while depletion of CCDC25, ILK, or β-parvin reduced Rac1/cdc42 activation." (PMID 35804980, 2022). "Stiff matrices, coupled with hypoxia result in a synergistic increase in ILK expression, coupled with increased expression of CSC markers and increased motility by breast cancer cells, suggesting that these environmental stressors potentiate ILK signaling to promote metastasis." (PMID 35804980, 2022). "The relative stiffness of the ECM and the presence of hypoxia, two critical features of the TME in solid tumors such as breast cancer, interact through ILK signaling to synergistically potentiate cancer stem cell (CSC) marker expression, tumor growth, and metastasis." (PMID 35804980, 2022). "However, the expression level of ILK was not only correlated with the sensitivity of GDC-0941 but also affected the sensitivity of breast cancer cells to GDC-0941." (PMID 35477364, 2022). "Recent unbiased, genome-wide investigations to identify potential targets for combination therapies centered on Src inhibitors identified ILK, in association with α-Parvin and PINCH-1 as a central determinant of sensitivity to the Src/Abl kinase inhibitor, bosutinib in breast cancer." (PMID 35804980, 2022).
breast cancer (continued). "Thus, ILK appears to be an important factor affecting the pathogenesis, progression, and prognosis of breast cancer." (PMID 35379935, 2022). "ILK inhibition also partially reverses EMT in MDA-MB-321 breast cancer cells." (PMID 35804980, 2022). "Previous experiments found that increased expression of ILK could lead to breast cancer cell line resistance to GDC-0941." (PMID 35477364, 2022). "The silencing of ILK in breast cancer cells significantly decreased liver metastases." (PMID 34067437, 2021). "This is significant because ILK promotes cancer progression in breast cancer models." (PMID 34205051, 2021). "What is more, emodin restrained EMT through the ILK/AKT/mTOR signalling pathway in breast cancer." (PMID 33531984, 2021). "The results show that, indeed, disruption of cellular microtubules by MTAs used in the treatment of breast cancer affects the biogenesis and secretion of sEVs as well as specific sEV cargos, including ILK, with differences noted between microtubule stabilizers and microtubule destabilizers." (PMID 34205051, 2021). "Furthermore, in breast cancer cells, an ILK-Rictor complex regulates TGF-β function for EMT induction and this complex is absent in normal cells." (PMID 34163519, 2021). "Similarly, exosomal transfer of ILK between breast cancer cells and normal mammary epithelial cells is significant in mammary tumorigenesis." (PMID 33672100, 2021). "Here, we reviewed the current literature on the role of ILK in breast cancer (BC)." (PMID 33043811, 2020). "The results show that ILK specifically predicts improved RFS in Luminal A breast cancers." (PMID 33276802, 2020). "Furthermore, mammary epithelial disruption of ILK in mice results in a profound block in mammary tumor induction." (PMID 33043811, 2020). "Next, the ILK inhibitor cdp-22 was used to treat HER-2-overexpressing breast cancer cell lines." (PMID 27391337, 2016). "Moreover, ILK expression has an impact on ErbB2-driven mammary tumor onset, and disruption of ILK inhibits proliferation and invasion and sensitizes ErbB2 tumor cells to apoptotic cell death." (PMID 25606594, 2014). "Furthermore, the activity of ILK has been linked to EMT and breast cancer progression." (PMID 34205051, 2021). "Ras Suppressor-1 (RSU-1), a cell-ECM adhesion protein that interacts with PINCH-1, thus being connected to Integrin Linked Kinase (ILK), alpha-parvin (PARVA), and actin cytoskeleton, is up-regulated in metastatic breast cancer (BC) samples." (PMID 31296919, 2019). "In particular, integrin-linked kinase (ILK), ER regulator PELP-1 protein, and the formation of a multiprotein complex between ERα, Src, PI3K, and the actin-regulator focal adhesion kinase (FAK) have been suggested as crucial players in the invasion and motility of breast cancer." (PMID 30189583, 2018). "Indeed, ILK/Akt pathway has been shown to be involved in breast cancer, prostate cancer and glioma." (PMID 21347395, 2011). "In addition, our research also raises the possibility of a more general role for ILK in cell-cell fusion per se as this fusion process has been suspected in breast cancer cells and demonstrated in macrophages and myoblasts – and all of which can highly express ILK." (PMID 19463178, 2009). "Taken together, GDC-0941 increased ILK level by upregulating TNF-α, thus affecting AKT expression and the sensitivity of breast cancer cells to GDC-0941." (PMID 35477364, 2022). "OSU-T315, an ILK inhibitor, was used in combination with GDC-0941 to analyze the effect on breast cancer cells." (PMID 35477364, 2022). "GDC-0941 synergistically inhibits tumor growth with ILK inhibitor or TNF-α antibody and has good anti-breast cancer effects." (PMID 35477364, 2022). "However, the effect of ILK on the drug resistance of GDC-0941 in breast cancer is unknown." (PMID 35477364, 2022). "Especially in breast cancer, increased amounts of Fibronectin activate the FAK/ILK/ERK/PIK/NK-κB signaling pathway and hereby mediate an up-regulation of MMP-2 and -9." (PMID 32560557, 2020).
breast cancer (continued). "RSU1 expression is higher in some of the basal type breast cancer cell lines; PINCH1 RNA is also increased in basal cell lines but there is less variability detected for ILK and parvin." (PMID 32751711, 2020). "They reported a significant acceleration in mammary tumor incidence and growth in the resulting MMTV-Wnt/ILK mice." (PMID 33043811, 2020). "A parallel study of integrin expression in the PMC42-ET breast cancer cell line induced to undergo EMT with EGF indicated that ITGA2 and ITGB1, and their downstream regulator ILK, appeared to be upregulated." (PMID 33276802, 2020). "A significant acceleration in mammary tumor incidence and growth was observed in the MMTV-Wnt/ILK mice." (PMID 20565980, 2010). "We observed a significant difference in the growth rate of the mammary tumors between MMTV-Wnt1 and MMTV-Wnt/ILK transgenic mice." (PMID 20565980, 2010). "In our model, initial immunohistochemistry revealed a greater presence of CD24-positive cells in both mammary tumors and pre-neoplastic mammary glands of MMTV-Wnt/ILK mice compared with the same tissue type in MMTV-Wnt mice (data not shown)." (PMID 20565980, 2010). "Because ILK links tumor cell‐intrinsic programs with microenvironmental support, it represents both a marker of TME influence and a potential therapeutic target in breast cancer." (PMID 41537745, 2026). "ILK/Rictor complex is reportedly formed constitutively in breast cancer cells but not in normal epithelial cells." (PMID 35982899, 2022). "Studies have shown that hypoxia stimulates the release of sEV from breast cancer cells and these sEV interact with neighboring normal MEC to drive several malignant changes, including stimulation of ILK-Akt signaling, turnover of FA, and enhanced motility of epithelial cells." (PMID 35804980, 2022). "Clinically, high levels of expression of ILK and YAP are correlated with poor prognosis in breast cancer and glioma, while heightened expression of an ETAR/ILK/YAP/AP-1/ZEB1 gene signature is correlated with significantly shortened survival in a cohort of SOC patients." (PMID 35804980, 2022). "It has been found that ILK mediates activation of YAP/TAZ, a co-transcriptional activator involved in the development of drug resistance, and thereby promotes tolerance to doxorubicin of breast cancer cells." (PMID 35089438, 2022). "Although the EMT-associated ITGB1, ITGA2 and ILK are not essential for EGF-induced EMT in PMC42-ET cells, they are necessary for breast cancer cell adhesion to ECM-substrates and cellular movement." (PMID 33276802, 2020). "Also, a significant acceleration in mammary tumor incidence and growth was observed in the MMTV-Wnt/ILK mice compared to mice expressing Wnt alone, showing the cooperation between Wnt1 and ILK genes during mammary carcinogenesis." (PMID 33043811, 2020). "Assessment of ITGA2/B1 and ILK expression in a published Luminal breast cancer dataset was not consistent with the pro-aggressive implications of our association with EMT in the EDW-01 PDX, since ILK predicted improved regression-free survival post treatment." (PMID 33276802, 2020). "Since DDR1 was shown to induce cell signaling, e.g., via the IGF axis in breast cancer, the insensitivity of W1CR cells to ILK inhibition could thus be explained." (PMID 31779287, 2019). "Higher transcript levels of ILK have been found in human breast cancer tissue compared to adjacent nondiseased breast tissue." (PMID 28391240, 2017). "Treatment with emodin (1,3,8‐trihydroxy‐6‐methylanthraquinone), promotes a MET process by targeting ILK in ovarian cancer and endometrial sarcoma cells, in addition to reducing EMT through the ILK/AKT/mTOR signaling pathway in breast cancer cells." (PMID 28590039, 2017). "It is possible that breast cancer cells can engage multiple pathways (PKC-zeta, ILK, Akt, Rac, and others) to regulate tumor cell metastasis, and it is interesting to speculate that Rictor may lie at the intersection of each of these pathways." (PMID 26132202, 2015).
breast cancer (continued). "Previous study showed that syntenin positively regulates the ILK adaptor function for the assembly of integrin β1/IPP signaling complexes, which activate integrin signaling pathways, including AKT, ERK1/2, and Rac1, in breast cancer cells." (PMID 23786877, 2013). "Recent evidence suggests that ER extranuclear signaling utilizes the ILK axis; therefore, ILK inhibitors such as QLT-0267 could be used to curb motility of breast cancer cells." (PMID 22295247, 2012). "Alternatively, helical or kinase domain mutants may activate a different set of PIP3 targets such as ILK or SGK3, an estrogen-regulated AGC family kinase that is required for survival of the ERα-positive breast cancer cell line MCF7." (PMID 21646685, 2011). "About half of the bi-transgenic mice examined (n = 23) developed palpable mammary tumors by the age of 19 weeks (T1/2 = 19), whereas fewer than 30% of the Wnt1 transgenic and none of the ILK or FVB control mice had tumors." (PMID 20565980, 2010). "Furthermore, in breast cancer cell lines SKBR-3 and MDA-MB-453, anoikis resistance can be restored by induction of ILK, independently of Akt activity." (PMID 15829011, 2005). "Consequently, the therapeutic vulnerability to ILK inhibition is not universal but is profoundly influenced by the cellular context, specifically the breast cancer subtype and the originating stromal cell driving ECM remodeling." (PMID 41537745, 2026). "Interaction between ILK and Rictor seems to be crucial in TGF-β-mediated EMT, since its prevention, either by silencing of ILK expression or by applying the ILK inhibitor, blocks this process and even partially reverses the mesenchymal phenotype in breast cancer cell lines." (PMID 35089438, 2022). "We coupled this with an investigation into the pattern of ILK and integrin expression changes in PMC42-ET human breast cancer cells induced by epidermal growth factor (EGF) treatment to undergo an EMT in vitro, and assessed whether these integrin changes were necessary for EMT to occur." (PMID 33276802, 2020). "We also found ILK knockdown to have the same effect on MUC1-C expression in two other cancer cell lines, including DU-145 prostate cancer and MDA-MB-231 breast cancer cells, revealing that the suppressive effect of ILK depletion on MUC1-C expression was not a cell line-specific phenomenon." (PMID 28692035, 2017). "In addition, we provide unanticipated, novel evidence suggesting cooperation between the Wnt1 and ILK pathways, resulting in upregulation of FOXA1/ER-α transcriptional network and the expansion of the luminal progenitor cells, leading to accelerated breast cancer development." (PMID 20565980, 2010). "It has been demonstrated in mammary epithelial cell lines that overexpression of ILK leads to the suppression of anoikis in a PKB/Akt-dependent manner and these phenomenon has also been shown to occur in various cancer cell lines such as breast cancer and prostate cancer." (PMID 23675014, 2007). "Therefore, the Wnt1/ILK-mediated upregulation of nuclear β-catenin shown both in vitro and in vivo could potentially be responsible for the observed upregulation of FOXA1 expression in the Wnt1/ILK mammary tumors." (PMID 20565980, 2010).